IGHV3OR16-13 (immunoglobulin heavy variable 3/OR16-13 (non-functional))
Synonyms: IGHV3/OR16-13
Gene: Immunoglobulin variable (V) gene on chromosome 16 (33,827,214 to 33,827,661, forward strand). Ensembl gene ENSG00000271178.
Gene Ontology:
Molecular function: antigen binding
Biological process: immunoglobulin mediated immune response
Cellular component: extracellular region; plasma membrane
Homologues: Orthologues: chimpanzee IGHV3OR16-13 (99% identical). Paralogues in human: IGHV3-74 (97% identical), IGHV3-64 (87% identical), IGHV3-23 (86% identical), IGHV3-48 (85% identical), IGHV3-7 (85% identical), IGHV3OR16-10 (85% identical), IGHV3-66 (85% identical), IGHV3-21 (84% identical), IGHV3-33 (84% identical), IGHV3-64D (84% identical), IGHV3-11 (83% identical), IGHV3-20 (83% identical), and 65 more.